MOB3C (MOB kinase activator 3C)
Description:
May regulate the activity of kinases.
Synonyms: MOBKL2C; MOB1E
Tractability: No criterion of Open Targets' tractability assessment is met for any kind of drug.
Gene: Protein-coding gene on chromosome 1 (46,607,719 to 46,616,862, reverse strand). Ensembl gene ENSG00000142961.
Subcellular location (Human Protein Atlas): Cytosol; Intermediate filaments
Gene Ontology:
Molecular function: protein binding; protein kinase activator activity
Genetic constraint (gnomAD): Loss-of-function variants: 17 observed, 20.13 expected, observed/expected ratio (o/e) 0.84, 90% interval 0.58 to 1.27. The upper end of that interval is the gene's LOEUF score, 1.27, which puts it in group 5 of 6, group 1 being the genes least tolerant of losing a copy. Missense variants: 291 observed, 317.88 expected, observed/expected ratio (o/e) 0.92, 90% interval 0.83 to 1.01. Synonymous variants: 101 observed, 126.13 expected, observed/expected ratio (o/e) 0.8, 90% interval 0.68 to 0.94.
Homologues: Orthologues: chimpanzee MOB3C (100% identical), macaque MOB3C (100% identical), pig MOB3C (99% identical), dog MOB3C (99% identical), guinea pig MOB3C (98% identical), mouse Mob3c (98% identical), rat Mob3c (98% identical), rabbit MOB3C (96% identical), tropical clawed frog mob3c (81% identical), zebrafish mob3c (81% identical), Drosophila melanogaster Mob3 (66% identical), Caenorhabditis elegans mob-3 (61% identical). Paralogues in human: MOB3A (73% identical), MOB3B (72% identical), MOB1A (50% identical), MOB1B (49% identical), MOB2 (33% identical), MOB4 (19% identical).
Diseases named in the same sentence as MOB3C in open-access papers:
MOB3C is named in the same sentence as 6 diseases in open-access papers, as found by Europe PMC text mining. Sharing a sentence is not in itself a finding about the gene and the disease. The quoted sentences say what the papers report.
glioblastoma (1 paper, 2023). The most malignant astrocytic tumor (WHO grade IV). "MOB3A and MOB3C are upregulated in gliomas, and combined depletion of all three human MOB3 proteins halted the proliferation of a glioblastoma cell line in vitro and in vivo." (PMID 37536630, 2023).
MOB3C also shares sentences with these, for which no sentence is quoted: cancer (2 papers); COVID-19 (1); glioma (1); Salmonella Infections (1); tumour (1).